BRCA1 (BRCA1 DNA repair associated)
Diseases named in the same sentence as BRCA1 in open-access papers (continued):
Sharing a sentence is not in itself a finding about the gene and the disease.
breast cancer (continued). "To evaluate further the evidence for an association between AR CAG repeat length and breast cancer risk in BRCA1 and BRCA2 mutation carriers, we genotyped the polymorphism in a large series of female mutation carriers." (PMID 15743497, 2005). "Questions need to be addressed concerning the clinical effects of mutations in the BRCA1 gene, why some mutation carriers develop breast cancer, others develop ovarian cancer, and some develop both." (PMID 16229746, 2005). "We have described a haplotype associated with the BRCA1 gene that is associated with an approximately 20% increase in risk of sporadic breast cancer in the general population." (PMID 15743496, 2005). "Several studies have been undertaken to assess the role of the CAG repeat polymorphism as a modifier of breast cancer risk in BRCA1 and BRCA2 mutation carriers." (PMID 15743497, 2005). "Women with germline BRCA1 mutations who carry at least one AR allele with 28 or more repeats have been reported to have an earlier age at onset of breast cancer." (PMID 15743497, 2005). "We also found that in the subgroup of BRCA1 mutation carriers who gained 10 pounds or more and who had at least two full-term pregnancies, there was a 44% increase in their risk of breast cancer." (PMID 16168130, 2005). "The risk of breast cancer in women who inherit a germline mutation in the BRCA1 gene can be as high as 20% by the age of 40 and 50% by the age of 50 and as high as 13% by the age of 40 and 60% by the age of 50 in BRCA2 mutation carriers." (PMID 16079000, 2005). "In a study of familial and sporadic human breast cancers by Hedenfalk and co-workers, Storey and Tibshirani estimated 33% of the genes to be differentially expressed between BRCA1 and BRCA2 mutation positive tumors." (PMID 16018805, 2005). "Truncation mutations in the BRCA1 gene are high-penetrance, low-prevalence factors in risk of breast cancer." (PMID 15743496, 2005). "In this context, and particularly in highrisk families, the most important tumor suppressor genes associated with breast cancer are BRCA1 and BRCA2." (PMID 16389418, 2005). "Early reports of The Breast Cancer Linkage Consortium estimated a contralateral breast cancer cumulative risk of 50–60% at age 70 years in BRCA1 or BRCA2 mutation carriers." (PMID 16052221, 2005). "The aim of this study was to collect serial samples of nipple aspirate (NA) and ductal lavage (DL) fluid from women with germline BRCA1/2 mutations in order to create a biorepository for use in identifying biomarkers of breast cancer risk." (PMID 16457692, 2005). "The use of morphologic and immunohistochemical data has been previously suggested to provide a helpful and cost-effective tool for predicting BRCA1 mutation among young breast cancer patients." (PMID 15987451, 2005). "Although weight loss reduced the risk of breast cancer among carriers of either mutation, this association remained significant only for women with a BRCA1 mutation (OR = 0.35)." (PMID 16168130, 2005). "Only two studies have evaluated the association between anthropometric risk factors or physical activity and the risk of breast cancer in BRCA1 and/or BRCA2 carriers." (PMID 16168130, 2005). "The BRCA1 or BRCA2 mutation prevalence found among women with breast cancer and such family history was 13% (4/31)." (PMID 16389418, 2005). "At this level of risk reduction, SCM would have a greater effect on breast cancer rates in BRCA1/2 carriers than would total mastectomy if at least 50% of BRCA1/2 carriers chose preventive SCM." (PMID 16079000, 2005). "Our analyses provide no support for an association between AR CAG repeat length and breast cancer risk in either BRCA1 or BRCA2 mutation carriers." (PMID 15743497, 2005). "BRCA1/2 mutations predispose to early-onset breast cancer, especially after oral contraceptive (OC) use and pregnancy." (PMID 15756256, 2005).
breast cancer (continued). "Carriers of these mutations show almost the same penetrance for ovarian- and breast cancer and the penetrance is also high compared to most reported BRCA1 mutation carriers." (PMID 16229746, 2005). "In total, 5% of breast cancer cases are believed to be due to inherited genetic mutations; 10–11.7% of ovarian cancer cases are believed to be the result of breast cancer susceptibility one and two (BRCA1/2) mutations." (PMID 15583691, 2005). "Conversely, plans published after 2000 provide more information on genetic testing for inherited breast cancer susceptibility (BRCA1 and BRCA2 genes) as well as brief discussions of familial risk assessment." (PMID 15888219, 2005). "We have described a haplotype in the BRCA1 gene that was associated with an approximately 20% increase in risk of sporadic breast cancer in the general population." (PMID 15743496, 2005). "Our data show that CPM markedly reduces the risk of contralateral breast cancer among BRCA1 or BRCA2 mutation carriers with a history of breast cancer." (PMID 16052221, 2005). "It is noteworthy that, among the 11 BRCA1/2-related breast cancers with EGFR somatic mutations, eight (72.7%) were located exclusively in the stroma." (PMID 15841079, 2005). "In an independent study, in one BRCA1 linked family, the daughter of a patient diagnosed with ovarian cancer not only had bilateral breast cancer, but also uterine leiomyomata." (PMID 15918899, 2005). "In our review of the literature, only one primary breast cancer has been reported to occur in a cohort of 207 BRCA1/2 mutation carriers who opted for preventive surgery." (PMID 16079000, 2005). "The discovery of the breast cancer susceptibility genes BRCA1-2 has allowed a clearer identification of genetically related cases." (PMID 15996267, 2005). "Among the subgroup of BRCA1 mutation carriers who had at least two children, weight gain of more than 10 pounds between age 18 and 30 was associated with an increased risk of breast cancer diagnosed between age 30 and 40 (OR = 1.44, 95% CI 1.01–2.04)." (PMID 16168130, 2005). "We identified 14 missense mutations in 11 (45.8%) of 24 breast cancers from BRCA1/2 mutation carriers." (PMID 15841079, 2005). "This variant was subsequently found to be significantly associated with non-BRCA1/2 familial breast cancer, being present in 5.1% of cases and only 1.1% of controls (P=0.00000003)." (PMID 15700044, 2005). "Germline BRCA1 or BRCA2 mutations are associated with a markedly increased lifetime risk of developing breast cancer in female carriers." (PMID 16457692, 2005). "There is accumulating evidence, both epidemiological and histological, that tumours arising as a result of mutations in the two breast cancer susceptibility gene families (BRCA1 and BRCA2) are biologically distinct." (PMID 15714204, 2005). "The data were obtained from Stanford-type cDNA microarrays, monitoring 2,654 genes across 22 breast cancer samples, 7 of which were found to carry germline BRCA1 mutations." (PMID 16207359, 2005). "Re-expression of BRCA1 in HCC1937 BRCA1-deficient breast cancer cell resulted in the repression of 21 transcripts." (PMID 15383145, 2004).
breast cancer (continued). "In particular, germ line mutations in BRCA1 have been identified in 15–20% of women with a family history of breast cancer and 60–80% of women with a family history of breast and ovarian cancer." (PMID 15353005, 2004). "Because some studies suggest that the CHEK2 1100delC variant acts as a breast cancer modifier in non-BRCA1/BRCA2 families only, we considered the subset of women known not to be BRCA1 or BRCA2 germline mutation carriers." (PMID 15535844, 2004). "Women with a BRCA1/2 mutation have a high lifetime risk for breast cancer (56–85%) and/or ovarian cancer (16–63%)." (PMID 14735173, 2004). "In only 7.5% of the sporadic patients diagnosed with breast cancer at young age, BRCA1/2 mutations were identified." (PMID 15026808, 2004). "A total of 18 families, 12 of which were at high risk of having hereditary breast cancer, have been examined for mutations at the BRCA1 locus." (PMID 15353005, 2004). "Up to 15–30% of women aged less than 35 years diagnosed with breast cancer are likely to have germ-line BRCA1 or BRCA2 mutations." (PMID 15546499, 2004). "The lifetime risk of breast cancer in female carriers of a BRCA1 mutation is 60–80% while that of ovarian cancer is 20–40%." (PMID 15353005, 2004). "It has been found that this procedure reduces the risk of ovarian cancer by 96% and breast cancer by 53% in BRCA1 or BRCA2 mutation carriers." (PMID 15083174, 2004). "The model predicts that among women who develop breast cancer at age 30 years, approximately 10% carry a BRCA1 or a BRCA2 mutation." (PMID 15381934, 2004). "Testing the combinatorial effects of Rb loss and other breast cancer mutations (e.g., BRCA1 and BRCA2), along with the further characterization of WAP-T121 tumors, should help provide additional insights into human breast cancer biology." (PMID 14966529, 2004). "Germline mutations of the tumour suppressor gene BRCA1 are involved in the predisposition and development of breast cancer and account for 20–45% of all hereditary cases." (PMID 12698198, 2003). "This study would suggest that in sporadic breast cancer cases the overproduced BRCA1 species is the Δ11b splice variant." (PMID 12698194, 2003). "We demonstrate cytoplasmic localisation in sporadic breast cancer suggesting excess Δ11b splice variant production, reduced production of full-length BRCA1 and thus postulate reduced tumour suppressor activity." (PMID 12698194, 2003). "This theme was pursued in a study of BRCA1-linked breast cancers; breast tumours with deleterious BRCA1 mutations were analysed for Fhit expression by immunohistochemistry." (PMID 12771912, 2003). "The prevalence of breast cancer is similar for BRCA1 and BRCA2 mutation families (average 3.7 and 3.6 per family), but the former have a much greater risk of ovarian cancer (average 1.5 and 0.6 per family, respectively)." (PMID 12698193, 2003). "Germline mutations of BRCA1 gene have been identified in 15–20% of women with a family history of breast cancer and 60–80% with family history of both breast and ovarian cancer." (PMID 12698198, 2003). "Germline mutation in the putative tumour-suppressor gene BRCA1 is believed to account for close to half of familial breast cancers." (PMID 14583770, 2003). "BRCA1 germline mutations have been described in only a handful of sporadic breast cancer cases where they are likely to represent de novo mutations." (PMID 12698194, 2003). "The mean age at diagnosis of breast cancer in BRCA1 mutation carriers was 42.6 years (95% CI 40.5–44.8)." (PMID 12698193, 2003). "In sporadic breast cancer however, it appears that an excess of BRCA1 Δ11b splice variant is produced, perhaps signifying the malfunction of this physiological control mechanism." (PMID 12698194, 2003). "The resulting model provides a framework for risk estimation to counsel women with a family history of breast cancer, allowing one to estimate carrier probabilities (separately for BRCA1 and BRCA2) and incidence rates in the same analysis." (PMID 11857015, 2002).
breast cancer (continued). "Under our best fitting model the breast cancer risk for BRCA1 carriers, based on the average incidence over all modifying effects, was estimated to be 35.3% by age 70 years." (PMID 11857015, 2002). "The cumulative breast cancer risk for a BRCA1 mutation carrier, based on the observed incidence, was estimated to be 36.5% by age 70 years and the ovarian cancer risk 28.5%." (PMID 11857015, 2002). "The relative risk of breast cancer as compared with the population incidence rates decrease sharply with age for BRCA1 mutation carriers, from 23.88 in the 30–39 year age group to 2.31 in the age group 60–69 years (Ptrend=0.005)." (PMID 11857015, 2002). "Out of all breast cancer patients 2% have a strong genetic predisposition, caused by highly penetrant genes (BRCA1 and BRCA2)." (PMID 12454765, 2002). "We found that the breast cancer incidence rates in BRCA1 mutation carriers relative to the population incidence rates decrease sharply with age." (PMID 11857015, 2002). "The cumulative breast cancer risk in BRCA1 mutation carriers over all modifiers is estimated to be 35.26% by age 70 years." (PMID 11857015, 2002). "There was also significant evidence for a modifying effect of other genes on the risks of breast cancer in BRCA1 and BRCA2 mutation carriers." (PMID 11857015, 2002). "The breast cancer patients with a BRCA1/2 mutation were significantly more radiosensitive (μ=1.28±0.24 (SD)) than the controls but not significantly different from the other two subgroups (unpaired t-test)." (PMID 12454765, 2002). "Selection of breast cancer patients with a mutation in BRCA1 or BRCA2 genes revealed a significantly higher mean value compared to the normal population only for the LDR MN assay." (PMID 12454765, 2002). "This was a case–control study comparing tamoxifen history in bilateral breast cancer patients with a BRCA1 or BRCA2 mutation with that in unilateral patients, also with a mutation." (PMID 11870509, 2002). "Based on these results the authors even suggest the application of the MN-assay as a screening test for carriers of a BRCA1 mutation in breast cancer families." (PMID 12454765, 2002). "In sporadic breast cancer, the majority of tumours are ER positive, whereas the opposite is the case in cancers diagnosed in women with high risk mutations in the BRCA1 and BRCA2 genes." (PMID 11870509, 2002). "In principle, however, breast cancer risk in BRCA1 positive women should be amenable to hormonal manipulation, since it has been shown that oophorectomy reduces risk in such women." (PMID 11870509, 2002). "Using the 90th percentile as a cut-off value, 27% of the breast cancer patients with a BRCA1/2 mutation were radiosensitive." (PMID 12454765, 2002). "Of the breast cancer susceptibility genes which have been identified to date, BRCA1 and BRCA2 are the most important ‘high risk’ genes accounting for the majority of families with multiple cases of breast and ovarian cancer." (PMID 11857015, 2002). "The polygenic model suggests that several genes, each having small but multiplicative effects on risk can account for the residual non-BRCA1/2 familial clustering of breast cancer." (PMID 11857015, 2002).
breast cancer (continued). "The breast cancer risk by age 70 years, based on the average incidence over all modifiers was estimated to be 35.3% for BRCA1 and 50.3% for BRCA2." (PMID 11857015, 2002). "A practical implication of these different age-incidence patterns, is that BRCA1 mutation carriers are more likely to develop breast cancer at a younger age than BRCA2 mutation carriers." (PMID 11857015, 2002). "About 5–10% of breast cancers are hereditary; a genetically and clinically heterogeneous disease in which several susceptibility genes, including BRCA1, have been identified." (PMID 11506493, 2001). "The aim of this analysis is to investigate the clinical and pathological features of these BRCA1 associated carcinomas as compared to other breast cancers in this representative sample." (PMID 11720473, 2001). "The aim of the present study is to molecularly classify BRCA1 mutated breast cancers by resolving gene expression patterns of BRCA1 and matched sporadic surgical breast tumour specimens." (PMID 11506493, 2001). "A previous study has suggested that BRCA1 carriers with longer lengths of the CAG repeat in the androgen receptor (AR) gene are at increased risk of breast cancer (BC)." (PMID 11437399, 2001). "Mutations of the BRCA1 or BRCA2 genes have been shown to strongly predispose towards the development of contralateral breast cancer in patients from large multi-case families." (PMID 11556836, 2001). "Three pathogenic BRCA1 mutations (Cys61Gly, 3814del5, 5382insC) were identified in the group of patients with unilateral breast cancer." (PMID 11556836, 2001). "Breast cancer susceptibility genes BRCA1 and BRCA2 are tumour suppressor genes the alleles of which have to be inactivated before tumour development occurs." (PMID 11710835, 2001). "Breast cancer penetrance by age 80 was estimated to be 48% (95% CI 7–82%) for BRCA1 mutation carriers and 74% (7–94%) for BRCA2 mutation carriers." (PMID 11044354, 2000). "Based on these results the estimated prevalence of breast cancer in the general population in the Netherlands attributable to BRCA1 mutations is 2.1%." (PMID 10952774, 2000). "The prevalence of BRCA1 mutations in Chinese patients with early onset breast cancer is similar to that observed in Caucasian women." (PMID 10682662, 2000). "BRCA1/2 mutation carriers diagnosed with breast cancer have a strongly elevated life-time risk of developing a contralateral tumour." (PMID 10917555, 2000). "The purpose of this study was to determine the prevalence of BRCA1 mutations in Chinese breast cancer patients in Singapore." (PMID 10682662, 2000). "We studied the contralateral breast cancer risk in 164 patients from 83 families with a proven BRCA1 mutation in relation to the age at diagnosis of the first primary breast cancer." (PMID 10917555, 2000). "Our series were composed of 16 cases of breast carcinoma in women with a germline Brca1 gene mutation, and of four cases with Brca2 mutation." (PMID 11044356, 2000). "Within the group of small breast-cancer-only families, a bilateral breast cancer case or a unilateral breast cancer case diagnosed before age 40 independently predicted finding a BRCA1 or BRCA2 mutation (P = 0.005 and P = 0.02, respectively)." (PMID 10188893, 1999). "The proportion of Australian women with breast cancer before age 40 who carry a germline mutation in BRCA1 was estimated to be 3.8% (95% Cl 0.3–12.6%)." (PMID 10408690, 1999). "The frequency, in women with breast cancer, of mutations and other variants in the susceptibility gene, BRCA1, was investigated using a population-based case–control-family study." (PMID 10408690, 1999). "We have screened for BRCA1 mutations in 230 women with breast cancer, all from the Wessex region of southern England, in order to establish the parameters on which to base a cost-effective regional mutation analysis strategy." (PMID 9649133, 1998).